HIF1A (hypoxia inducible factor 1 subunit alpha)
Diseases named in the same sentence as HIF1A in open-access papers (continued):
Sharing a sentence is not in itself a finding about the gene and the disease.
tumor (continued). "Although AR was already cytoplasmic 1 day after castration and the weight of the seminal vesicles was reduced after 3 days in both mouse lines (Fig EV2A–C), histological analyses revealed tumor regression in prostates of Pten/Hif1a(i)pe−/− mice but not in those of Pten(i)pe−/− ones." (PMID 37070472, 2023). "In TNBC cells, BHLHE41/DEC2 can bind and inhibit HIF-1α and HIF-2α functions by promoting their proteasomal degradation that is independent of the von Hippel–Lindau tumor suppressor, which is an E3 ligase of HIF-1α and HIF-2α proteins, and suppress tumor invasion and metastasis in an in vivo model." (PMID 37511489, 2023). "Interestingly, bimodal therapy completely abolished hypoxia, as seen in the number of HIF-1α-positive hypoxic tumor cells compared to those in non-treated tumors (p < 0.0001)." (PMID 38201461, 2023). "In addition, the chemical inhibitors targeting STAT3 and HIF-1α were dissolved in dimethyl sulfoxide, which is toxic and not suitable for use in the tumor xenograft model." (PMID 36814597, 2023). "HIF-1α has been proved to participate in the transcription of downstream target genes, such as VEGF, erythropoietin, and glucose transporter 1 gene, and activate multiple signaling pathways that lead to tumor cell proliferation, angiogenesis, invasion, and metastasis." (PMID 37333486, 2023). "HIF-1α promotes the upregulation of glycolytic enzymes and mono-carboxylate transporters (MCT-4) in CAA/CAFs, thereby increasing the production and transportation of mono-carboxylates (lactate, pyruvate, beta-hydroxy butyrate (β-HB)) into the tumour microenvironment." (PMID 37233716, 2023). "If HIF-1α and HIF-2α are upregulated simultaneously in TAMs, whether one isoform predominates over the other, and the temporal dynamics based on type of hypoxia (intermittent vs continuous) or tumor stage remain unclear." (PMID 37520562, 2023). "Moreover, the HIF-1α/VEGFR/Akt/eNOS signaling axis is upregulated under hypoxic conditions in tumors and contributes to cancer development and progression by promoting angiogenesis and EMT of tumor cells." (PMID 37400960, 2023). "IL-6 might induce tumor immunosuppression by decreasing effector T-cells by enhancing cancer glucose uptake and by increasing regulatory cells through HIF1α and VEGF function via hypoxia-pseudohypoxia-mediated HIF1α activation." (PMID 36764954, 2023). "Our data also support that altering HIF-1α expression in the large population of pro-tumoral hypoxic neutrophils may be an excellent target not yet exploited in tumor biology." (PMID 36614196, 2023). "Moreover, some of these drugs, including clodronate and pamidronate, inhibit angiogenesis by inhibiting vascular endothelial growth factor (VEGF) and hypoxia-inducible factor 1-alpha (HIF-1α), and others inhibit the adhesion, invasion, and migration of tumor cells." (PMID 38260135, 2023). "The immunohistochemistry results confirmed the SHMT2 knockdown efficiency in the tumor tissue, and the HIF1α staining results were consistent with the in vitro findings, indicating that the HIF1α in the shSHMT2 group was not normally expressed during tumor hypoxia." (PMID 37108312, 2023). "In addition, inhibition of HIF-1α and HIF-2α activity interferes with tumor growth and vascularization as well as reprogramming of the tumor immune microenvironment to promote anti-tumor immunity and improve the response to anti-programmed cell death protein 1 therapy." (PMID 38074679, 2023). "It is hypothesized that tumor necrosis results from cellular hypoxia mediated signaling, such as hypoxia-inducible factor-1α (HIF-1α) and the expression of carbonic anhydrase IX (CAIX), which results in tumor dedifferentiation, angiogenesis, and a more aggressive histological phenotype." (PMID 37190241, 2023). "Interestingly, we found that HIF1α expression, rather than HIF2α expression, was significantly decreased in tumor tissues of Brafm/+; Tet1−/− mice compared with that of Brafm/+; Tet1+/+ mice." (PMID 37020036, 2023).
tumor (continued). "During CRC development, HIF-1α binds to the SOX12 (SRY-box transcription factor 12) promoter to increase SOX12 expression, which further increases the SOX12-mediated expression of GLS and GOT2, leading to cellular metabolism adaptation that promotes tumor progression." (PMID 36755301, 2023). "Given that HIF-1α is of great importance in TAMs accumulating, the strategy of targeting MDSCs and M2-like macrophages through HIF-1α may be an effective method to inhibit tumor progression." (PMID 36675491, 2023). "Moreover, BRAFi significantly decreased the expression of HIF‐1α in D4M tumors, and the effect was maintained in combination with anti‐m‐VEGFA treatment but not after anti‐mVEGFA alone, indicating that BRAF inhibition is critical for abrogating tumor hypoxia." (PMID 37183363, 2023). "Besides, spheroid cells-generated tumors showed the cellular robust activity compared with parent cells tumor as proliferative-related protein PCNA, angiogenesis-related protein VEGF, CSC-related protein CD133 and HIF-1α displayed significantly increased expressions in spheroid cells induced tumors." (PMID 37143105, 2023). "Intra-tumoral heterogeneity in hypoxia and a non-homogenous distribution of drugs within the tumor mass may pose further limitations to the effect of HIF-1α inhibitors." (PMID 36846589, 2023). "In addition, HIF-1α, HK2, and PKM2 were greatly accumulated in tumor-infiltrating DCs." (PMID 36821379, 2023). "Therefore, it is reasonable to hypothesize that miR-873-5p may serve as a tumor suppressor in GBM with the involvement of HMOX1, HIF1α and SPOP." (PMID 37382594, 2023). "Immunoblotting of tumor lysates showed an obvious reduction in MCL-1 levels in the MCL-1 knockdown group, but little effect on AKT/ HIF-1α pathway molecules while compared with vehicle treatment group, suggesting that MCL-1 acts as a downstream factor in the AKT/ HIF-1α signaling pathway." (PMID 35136016, 2022). "However, both HIF-1α and HIF-2α show promoting effects on ferroptosis in CCCs, suggesting the regulation of ferroptosis by HIF is complex and can be affected by many factors such as tumor types, metabolic levels and external environment." (PMID 35624785, 2022). "Much like the knockdown of Hif1a, loss of Pdl1 (sh-Pdl1) in E0771 cells also inhibited tumor growth in C57BL/6, but not NSG, recipients, and LEM did not further suppress sh-Pdl1 E0771 tumor growth in C57BL/6 or NSG recipients." (PMID 35239514, 2022). "Moreover, although inhibition of HIF1α, HDAC1, or EZH2 in immune cells can restore immune cytotoxicity, it also paradoxically induces PD-L1 and PD-L2 expression in tumor cells that in turn could weaken anticancer immunity." (PMID 35840558, 2022). "Furthermore, HIF-1α and HIF-2α display opposite functions, where target genes of HIF-1α correlated with improved survival and decreased tumor growth while HIF-2α target genes correlated with a worse prognosis and increased tumor growth." (PMID 35267567, 2022). "It was observed that after Gossypol treatment, the cell viability of COLO225 which is a human colon cancer line, was significantly reduced along with downregulation of HIF1A, GLUT1, and GAPDH, indicating that Gossypol could inhibit tumor growth partly through glycolytic pathways." (PMID 36319992, 2022). "Here, we report that freshly isolated NK cells from human peripheral blood in hypoxia could not stabilize HIF-1α protein coincident with impaired anti-tumor cytotoxicity." (PMID 34999917, 2022). "This is related to HIF1α and HIF2α accumulation and overexpression of genes related to hypoxia response such as VEGF (Vascular Endothelial Growth Factor), PDGF (platelet derived growth factor) and others leading to promotion of angiogenesis, tumour growth and survival." (PMID 35106125, 2022).
tumor (continued). "Interestingly, in both tumor subgroups, we found a marked BIRC5 overexpression compared to the control samples, even though a very strong and significant positive correlation between HIF1A and BIRC5 was observed only in the KDM5CHigh subgroup." (PMID 36142158, 2022). "In addition, TACE could lead to necrosis of tumor tissue and upregulate the expression of hypoxia-inducible factor 1-α (HIF-1α), vascular endothelial growth factor (VEGF), and fibroblast growth factor (FGF), which could stimulate tumor recurrence or growth." (PMID 36249023, 2022). "Such discrepancies serve to highlight the problematic heterogeneity (e.g. tumour downstaging or tumour regression) encountered in this field when attempting to draw conclusions, thus explaining why HIF-1α is, to date, not used as a clinically useful prognostic biomarker in RC." (PMID 36032656, 2022). "Most specimens represented chemotherapy-naive tumour and results might have been confounded by other mechanisms that control TUBB3 expression, such as hypoxia via transcription factors HIF-1α/HIF-2α epigenetic modifications or differences in warm ischaemia time and treatments rendered." (PMID 35149854, 2022). "HIF-1α is one of the two subunits of hypoxia-inducible factor-1 (HIF-1), which after activation plays a crucial role in the adaptive response of tumor cells growth by stimulating the overexpression of glucose transporters (GLUTs) involved in meeting the energetic needs of tumor cells." (PMID 35887090, 2022). "In macrophages, GC treatment was shown to promote genes involved in the tricarboxylic acid (TCA) cycle but inhibit glycolysis by suppressing hypoxia-inducible factor 1-alpha (HIF1α); however, how this impacted anti-tumor CD8+ T cell responses was not investigated." (PMID 36337733, 2022). "Moreover, virus-mediated overexpression of miR-199 and miR-34a has been found to lead to control of tumor growth by targeting mTOR, c-MET, HIF-1α, and CD44, as well as complete tumor regression by targeting Bcl-2 and SIRT1 in xenograft murine models of HCC, respectively." (PMID 35954176, 2022). "Inspection of these markers in regions of elevated CD73 showed that HIF1A, GLUT1, and ARG1 were enriched in tumor cells adjacent to regions of palisading necrosis, again suggesting that hypoxia may promote the expression of CD73 in neighborhoods that drive immunomodulatory signaling." (PMID 35973991, 2022). "HIF-1α decreases the level of MYC by inducing the transcription of MAX interactor 1 (MXI1) (a repressor of MYC) in cancer cells and enhances mitochondrial respiration but increases the glycolysis, leading to tumor growth and survival in a low oxygen environment." (PMID 35798726, 2022). "The HIF‐1α expression of group 6 was only 33.28% of group 5, and the expression of group 3 was only 27.97% of group 2, showing the CAT loaded in DDRi@CAT‐PD‐M1Exos could obviously relieve tumor hypoxia." (PMID 35715382, 2022). "To determine whether the RNA data can be extended to protein expression levels in ccRCC, we performed immunohistochemistry (IHC) analysis using anti-SENP1, HIF1α, and HIF2α antibodies with a custom tissue microarray (TMA) containing 190 benign and 471 malignant ccRCC tumor samples." (PMID 36284084, 2022). "The downregulation of HIF-1α and carbonic anhydrase 9 (CA-IX) and increased vascular permeability after IRE suggest that IRE may also increase the number and action of local T cells, NK cells by alleviating tumor hypoxia." (PMID 36081554, 2022).
tumor (continued). "The nanozyme could catalyze the decomposition of intracellular H2O2 into oxygen for hypoxia relief as evidenced by the suppression of hypoxia-inducible factor-1α (HIF-1α), and moreover, GSH depletion and cell ferroptosis were also achieved for synergistic tumor therapy." (PMID 36109814, 2022). "Importantly, HIF-1α is found in both CSCs and non-stem tumor cells, while HIF-2α is exclusively found in CSC and not detected in the normal human macrophages, thus making it a potential great target for treatments." (PMID 35203636, 2022). "However, we also indicated and implied that HIF-1α and HIF-2α are diverse by nature, and proposed an alternative perspective to elucidate the role of HIF-α dynamics in tumor progression; that cancer optimizes the HIF pathway for tumor progression through balancing of the α-subunit." (PMID 35267567, 2022). "Recent studies have also revealed that the CH1 domain of CBP/p300 and the C-TAD of the HIF-1α complex is preferentially required for the expression of a multitude of hypoxic genes (GLUT-1, LDH-A, MCT-4, and VEGF) involved in cancer progression and adaptation to the hypoxic tumor microenvironment." (PMID 35592530, 2022). "Furthermore, Xing M demonstrated that activation of MAPK signaling pathway resulted in upregulation of tumor-promoting genes (e.g. VEGFA, MET, HIF1A, UPA, UPAR, TGFB1, and TSP1) as well as downregulation of tumor suppression and thyroid genes (e.g. TIMP3, SLC5A8, DAPK1, NIS, TSHR, and TPO)." (PMID 35600399, 2022). "According to the immunofluorescence analysis of tumour sections stained with CD31 and HIF-1α as well as the representative PA images and micro-PET scanning images, it was obvious that Endo@GOx-ER treatment resulted in vascular normalization and accomplished long-term tumour hypoxia relief." (PMID 36277398, 2022). "Moreover, suppressing HIF-1α and/or HIF-2α inhibited the enhanced growth rates of tumor cells, resulting from SdhB suppression, suggesting that ROS production and the subsequent activation of HIF-α were responsible for SdhB-induced tumor formation." (PMID 36671435, 2022). "This non-canonical crosstalk between HIF-1α and Notch may serve to promote tumour cellular undifferentiation and plasticity characterising VM-forming cells." (PMID 36224457, 2022). "Similarly, researchers utilized superparamagnetic iron oxide-based NPs (SPIONs) combined with chitosan lactate (CL) and folic acid (FA) nanoparticles (NPs) loaded with TIGIT-siRNA and HIF-1α-siRNA for suppressing TIGIT and HIF-1α in tumor cells in another study." (PMID 36532768, 2022). "In addition, HIF-1α sustains cell migration facilitating epithelial-mesenchymal transition (EMT) through Snail proteins and ECM remodeling and increasing tumor invasive potential by dysregulating glycosylation processes and altering the blood vessel permeability." (PMID 35682991, 2022). "Therefore, the hypoxic state following anti-angiogenic therapy may stimulate HIF-1α, which, in turn, activates VEGF-independent angiogenetic pathways, including FGF/FGFR, promoting tumor revascularization and, eventually, tumor progression." (PMID 36551599, 2022). "Interestingly, under hypoxic conditions, HIF-1α increases ALDOA expression, leading to increased lactate production and reducing the degradation of HIF-1α, subsequently promoting the invasive abilities of tumor cells." (PMID 35404841, 2022). "Intriguingly, we also found that hypoxia increases the expression of TP in supernates of neutrophils and macrophages, while in mice, circulating levels of this factor are positively correlated with tumor propagation in WT but not myeloid HIF1α KO or myeloid HIF2α KO mice." (PMID 36291563, 2022). "Tumor angiogenesis induced by gastric cancer-derived succinate is independent of HIF-1α." (PMID 36344992, 2022).
tumor (continued). "This RT-induced overexpression of PD-L1 by tumor cells can take place either via the production of IFN-γ by RT-activated T cells in immunogenic tumors, as well as in poorly immunogenic tumors where there is concomitant TGF-β blockade, or via RT-mediated upregulation of HIF-1α." (PMID 35681654, 2022). "Moreover, tumor cells display upregulation of GLUT1 and GLUT3 expression in response to HIF-1α." (PMID 35847943, 2022). "In ccRCC, the inactivation of VHL leads to the protein accumulation of HIF-1a and HIF-2a, which translocate to the nucleus and regulate a variety of gene expression programs at the transcriptional level to promote tumor growth, tumor metastasis, and neo-angiogenesis." (PMID 36611966, 2022). "In the mice described in the studies above, we observed positive correlations between the circulating levels of TP and tumor vascularisation, proliferation, number, and area in WT mice, but all of these correlations were absent in myeloid HIF1α KO or myeloid HIF2α KO littermates." (PMID 36291563, 2022). "Moreover, HIF-1α may play a central role in tumorigenesis by upregulating different signaling pathways such as Myc and PI3K/AKT/mTOR that are involved in tumor proliferation, differentiation, migration, and invasion." (PMID 35845307, 2022). "However, this study found that HNK has a definite relationship with UFL1 and BRE1B and can promote the combination of UFL1 and BRE1B with HIF-1α, which improves the ubiquitination degradation level of HIF-1α to a certain extent, and then reverses tumor growth via the glycolytic pathway." (PMID 35350760, 2022). "TAZ has been found to function as a coactivator of HIF1, via direct interaction with the transactivation domain of HIF1A, by which TAZ could direct HIF1 to the hypoxia response elements and contribute to the transcription of downstream genes, thereby promoting tumor cell survival and migration." (PMID 35012640, 2022). "However, hypoxia occurs during NSCLC tumor growth, and we found that hypoxia of NSCLC cells induced HIF1α competitive binding to SP1; this may relieve the SP1-Alu feedback suppression loop and increase circ-0001875 circularization." (PMID 35473752, 2022). "The decrease in APOE expression may promote tumor metastasis through NOTCH1, HIF1A, and TGFB1." (PMID 36428687, 2022). "This interaction between HIF1a and GLUT-1 could explain some cases of tumor heterogeneity." (PMID 35053598, 2022). "Not surprisingly, the malignant features of tumours, which expressed high HIF-1α levels were higher, and the selective inhibition of HIF-1α with natural degradation pathways that bypass the common PHD2 pathway could suppress these features." (PMID 35563576, 2022). "Overexpression of HIF1A and HIF2A also accelerates excretion of chemotherapeutic drugs from tumor cells and induce abnormal DNA damage repair in cells, thereby reducing the sensitivity of cells to chemotherapeutic drugs based on DNA damage, resulting in tumor multidrug resistance." (PMID 35659268, 2022). "Under hypoxic conditions, HIF1A induces activation of target genes (PD-L1, CCL28, and GAL3ST1), resulting in immune cell apoptosis, and drives expression of the negative immune checkpoint regulator VSIR and MIC genes to evade immune surveillance and ultimately promote tumor immune escape." (PMID 35659268, 2022). "HIF-1α and HIF-2α are highly homologous and they share many functional features overlapping, and yet they also exhibit significant differences in tissue-specific expressions and some physiological functions such as the regulation of anti-tumor immune responses." (PMID 35805044, 2022).